RXRA (retinoid X receptor alpha)
Diseases named in the same sentence as RXRA in open-access papers (continued):
Sharing a sentence is not in itself a finding about the gene and the disease.
leukemia (10 papers, 2005 to 2025). A malignant (clonal) hematologic disorder, involving hematopoietic stem cells and characterized by the presence of primitive or atypical myeloid or lymphoid cells in the bone marrow and the blood. "It was also found in leukemia cells that non-coding variants at KRAS and PER2 enhancers affect the binding of nuclear receptor family TFs PPARG and RXRA, which disturbs the expression of KRAS and PER2 and promotes the growth of leukemia cells." (PMID 39724337, 2025). "While the antiproliferative effect of RXR agonists is already used in leukemia treatment, the role of RXRα in myeloid cells regarding their local proliferation remains insufficiently understood." (PMID 35740296, 2022). "The analysis revealed the presence of RXRA (147 hits), a transcription factor required for leukemia development." (PMID 34832908, 2021). "For example, for GATA1, we found several cell-type specific co-regulators such as HNF1 in hematopoietic progenitor cells, PPARA:RXRA in leukemia and a general co-regulator EVI1 found to cooperate with GATA1 in more than 15 cell types." (PMID 30142147, 2018). "Additionally, it has been confirmed that the knockdown of RXRA can induce radiation resistance, and its deletion can promote leukemia growth in mice." (PMID 40781327, 2025). "For example, GATA1 partners with HNF1 in hematopoietic progenitor cells; with PPARA:RXRA in leukemia; with SRF, CDX and FOXP3 in primary T-cells; with SRY, NKX2-1, FOXF1, OCT4 and ZBTB16 in differentiated ESCs and with TAL1:TCF3 motif co-occurring in various fibroblasts." (PMID 30142147, 2018). "Moreover, a mutant form of RXRα disrupts proliferation in murine KMT2A-MLLT3 leukaemia cells." (PMID 39804120, 2025). "Furthermore, mouse and human leukemia cells could be distinguished from normal B-cells by their increased expression of Rarγ2 and RXRα, respectively." (PMID 29725010, 2018). "Transcription factor binding motif analyses in gene promoters divulged two transcription factors possibly regulating the expression of these genes, i.e., RXRA and GATA1, which are important for leukemia and erythroid development, respectively." (PMID 34832908, 2021).
metabolic syndrome (10 papers, 2013 to 2025). A cluster of metabolic risk factors for CARDIOVASCULAR DISEASES and TYPE 2 DIABETES MELLITUS. "A few studies have reported associations with SNPs or haplotypes within RXRA gene with plasma TG levels or the metabolic syndrome." (PMID 24647074, 2014). "A few studies have observed associations with plasma TG levels, coronary heart disease risk and metabolic syndrome with SNPs located within RXRA gene." (PMID 24647074, 2014). "We did not have detailed lipid profiles of women with ICP, which may show other associations between this RXRA gene variant and dyslipidemia in cholestatic patients." (PMID 40806580, 2025). "However, feeding RXRA knockout mice a high-fat diet can cause dyslipidemia." (PMID 36830469, 2023). "ENHO, RXRA, and LXRA SNPs were associated separately or jointly with dyslipidemia, MI, and survival in HD patients." (PMID 31775661, 2019). "However, serum LDL-cholesterol positively correlated with ENHO transcript and ENHO rs2281997 and RXRA rs749759 showed epistatic interaction concerning dyslipidemia diagnosed by LDL-cholesterol ≥100 mg/L." (PMID 31775661, 2019). "Tested transcripts did not correlate with gender, age, diabetic nephropathy, types of dyslipidemia, active HBV/HCV infection, liver enzyme activities but ALP with RXRA transcript, inflammatory state assessed by plasma C-reactive protein, or lipid-modifying treatment." (PMID 31775661, 2019). "Relative CASR transcript level positively correlates with dry body weight, RXRA, LXRA and ENHO transcripts, and RRT duration, but is not dependent on gender, age, diabetic nephropathy, types of dyslipidemia, or lipid-modifying treatment." (PMID 31775661, 2019). "There were no epistatic interactions between CASR and RXRA, LXRA, and ENHO regarding dyslipidemia." (PMID 31775661, 2019).
Insulin resistance (9 papers, 2017 to 2024). Increased resistance towards insulin, that is, diminished effectiveness of insulin in reducing blood glucose levels. "The rs2234753 SNP of the RXRA gene may have a positive effect on glucose metabolism, reducing insulin resistance; consequently, it mitigates the development of microvascular complications, such as neuropathy." (PMID 38339094, 2024). "Moreover, some studies reported DNA methylation profiles in several genes related to RXRA, SREBF1, PPARA, etc., closely associated with age-related susceptibility to hepatic insulin resistance and increased liver lipid metabolism." (PMID 37201099, 2023). "Although dibutyltins display some partial PPARγ/RXRα agonistic effects, the translation of cell-based results assays into in vivo effects on inflammation and insulin resistance is not entirely known." (PMID 28824431, 2017).
melanoma (9 papers, 2009 to 2024). A malignant, usually aggressive tumor composed of atypical, neoplastic melanocytes. "Together, these results indicate that ablation of keratinocytic Rxrα expression consequences in an alteration of distinct important key signaling pathways involved in the melanoma microenvironment that elevates melanoma susceptibility." (PMID 29121869, 2017). "Loss of RXRα in the epidermal keratinocytes in combination with oncogenic NRASQ61K and CDK4R24C/R24C mutations in trigenic mice led to significant melanoma invasion into the draining lymph nodes as compared to controls with functional RXRα." (PMID 29121869, 2017). "A progressive loss of keratinocytic RXRα protein was observed through analysis of human melanomas collected at different stages of disease progression starting from benign nevi to melanoma in situ and invasive and metastatic melanomas." (PMID 29121869, 2017). "In malignant human melanomas, loss of RXRα expression has been previously reported both in the melanoma cells themselves and in the adjacent epidermal keratinocytes." (PMID 24810760, 2014). "Furthermore, loss of keratinocytic Rxrα expression when combined with activated Cdk4R24C/R24C or oncogenic human NRAS (Tyr-NRASQ61K) after chronic UVB-irradiation results in malignant melanoma formation." (PMID 29121869, 2017). "Whether these changes enhance susceptibility to melanoma and other types of skin cancer in the long-term, need to be further examined in future using chronic or intermittent UV exposure of the Rxrα/βmel−/− mice." (PMID 24810760, 2014). "Loss of expression of RXRα has been previously reported during melanoma progression in humans." (PMID 24810760, 2014). "Interestingly, we observed a significant increase in p21 and Cyclin D1 in the TAN skin of un-irradiated trigenic RXRαep−/− mice, suggesting that those changes might be consequences of loss of functional RXRα in the melanoma microenvironment." (PMID 29121869, 2017). "A histological analysis of RXRα expression throughout melanoma progression indicates that its nuclear expression decreases between benign nevi and the primary tumor." (PMID 35326683, 2022). "Above results argue for its anticancerogenic role and suggest a cell-autonomous role of melanocytic RXRα in melanoma suppression." (PMID 34692525, 2021). "In the same report, primary human melanoma samples exhibited significantly higher cytoplasmic expression of RXRα compared to the nevi (P = 0.018) or the melanomas with metastasis and in metastasis samples (P = 0.004)." (PMID 34692525, 2021). "The draining lymph nodes of trigenic Rxrαep−/− mice showed an increased number of melanoma cells invasion compared to the controls with functional RXRα." (PMID 29121869, 2017). "In this study, we investigated the role of keratinocytic RXRα in spontaneous and acute neonatal UVB induced melanoma formation as this is a more biologically-relevant model since malignant melanoma is epidemiologically associated with acute sun exposure." (PMID 29121869, 2017). "The percentage of dermal TUNEL positive cells in trigenic mice was reduced compared to the controls both in the untreated and single UVB treated group suggesting that keratinocytic RXRα plays a role in regulating apoptosis in the dermal melanomas." (PMID 29121869, 2017). "A significant increase in RGP and VGP is observed when RXRα is lost in the epidermal keratinocytes in the trigenic mice where melanoma formation is seen spontaneously, and a single neonatal UVB exposure aggravates this effect." (PMID 29121869, 2017). "This will allow us to understand the contribution of epidermal RXRα in melanoma formation together with aberrant signaling pathways such as MAPK and CDK4 and after a single neonatal UVB exposure." (PMID 29121869, 2017).
melanoma (continued). "Our results suggests that keratinocytic RXRα has a protective role against aggressive melanoma formation induced spontaneously or after acute UVB irradiation." (PMID 29121869, 2017). "We have also demonstrated that knocking out of epidermal RXRα in conjunction with oncogenic mutant NRASQ61K or activated Cdk4R24C/R24C promotes chronic UVB-induced melanoma formation." (PMID 29121869, 2017). "Expression of type II nuclear receptor Retinoid-X-Receptor α (RXRα) is lost during melanoma progression in humans." (PMID 24810760, 2014). "Moreover, loss of keratinocytic RXRα, a dimeric partner of VDR, combined with activated CDK4 or oncogenic NRAS generated UVB-induced melanomas." (PMID 38927967, 2024). "It has also been reported that both NRF2 and ROS, in turn, negatively regulate RXRα expression, which might explain why it is reduced during melanoma progression." (PMID 35326683, 2022). "Following acute neonatal UVB irradiation, melanomas in adult keratinocytic RXRα ablated mice had increased radial and vertical growth phases, increased proliferation, increased angiogenesis, reduced apoptosis, and increased metastasis to the draining lymph nodes." (PMID 34692525, 2021). "Altogether, our results indicate that ablation of keratinocytic RXRα in combination with driver mutations such as NRASQ61K and Cdk4R24C/R24C, abets the formation of spontaneous melanomas that are malignant in nature and these effects are further exacerbated by a single neonatal UVB exposure." (PMID 29121869, 2017). "Also, epidermis-specific ablation of RXRα in a mouse model was shown to promote melanocyte proliferation after UV radiation (UVR) and increased susceptibility to malignant melanomas after a multi-stage carcinogenesis treatment." (PMID 24810760, 2014). "Here we report that the trigenic mice develops spontaneous melanoma and exposure to a single neonatal UVB treatment reduces the tumor latency in those mice compared to control mice with functional RXRα." (PMID 29121869, 2017). "A significantly higher percent of cells from benign human nevi samples exhibited nuclear localization and strong expression of RXRα (P < 0.0001) compared to melanomas (with or without metastasis)." (PMID 34692525, 2021). "With this mouse model we observed the formation of spontaneous melanomas in the absence of UVB when keratinocytic RXRα was ablated." (PMID 34692525, 2021). "Altogether, above results indicate that abrogating Rxrα expression in the epidermis in combination with activated CDK4 and N-RAS contributes to enhanced proliferation, malignant conversion, and vascularization of melanomas, and exposure to a single neonatal dose of UVB accelerates this process." (PMID 29121869, 2017). "It is possible that together with enhanced post-UVR melanocyte survival in absence of RXRα/β, the decreased post-UVR survival of fibroblasts we observe may encourage proliferation and propagation of dermal melanomas." (PMID 24810760, 2014).
liver cancer (8 papers, 2008 to 2025). An epithelial or non-epithelial malignant neoplasm that arises from the liver. "The change in hepatic cancer-related gene expression profiles due to RXRα deficiency was gender- and age-dependent." (PMID 18755030, 2008). "The alteration of mRNA levels of cancer-related genes implied that aberrant RXRα signaling could potentially increase the risk of liver cancer and that retinoid signaling might contribute to gender- and age-associated liver cancer incidence." (PMID 18755030, 2008). "While RXR agonists impair HBV infection in liver cancer cell lines and primary hepatocytes, reduced RXRα expression increases HBV infectivity." (PMID 41276823, 2025). "To elucidate the molecular mechanisms underlying the overexpression of TRIM71 in liver cancer cells, we analyzed potential regulators binding on TRIM71 promoter regions using ENCODE database, and unexpectedly discovered the potential binding of retinoid X receptor alpha (RXRA) factor and EP300." (PMID 39267787, 2024). "Although 24 month old hepatocyte RXRα-deficient mice do not develop spontaneous liver cancer, our data implied that hepatocyte RXRα-deficient mice might be more susceptible to cancer development, and this increased risk might be gender- and age-dependent manner." (PMID 18755030, 2008). "Importantly, ATRA or A-485 decreased mRNA levels of TRIM71, CEBPA, PSPH, PSAT1 and protein levels of TRIM71 and CEBPA, suggesting the transcriptional regulation of RXRA and EP300 to TRIM71 in liver cancer." (PMID 39267787, 2024). "As TRIM71 is vital for maintaining the dedifferentiation of stem cells and regulate glycine/serine metabolism, we hypothesized the potential regulation of RXRA and EP300 on TRIM71 in liver cancers." (PMID 39267787, 2024).
cardiac hypertrophy (7 papers, 2016 to 2024). "The several main regulators of PPARα such as HSF-1, ATGL, RXRα, and ERRα were detected, the downregulation of which are associated with cardiac hypertrophy." (PMID 35479323, 2022). "Along these lines, experiments in rodents indicated that treatment with NAD and the RXRα agonist bexarotene protected against cardiac hypertrophy via activating LKB1-AMPK signaling." (PMID 35592411, 2022). "Among them, five signaling pathways, such as PPAR and PPARα/RXRα activation, were significantly downregulated, and the cardiac hypertrophy signaling, pulmonary fibrosis idiopathic signaling pathway, and S100 family signaling pathway were significantly upregulated." (PMID 39202454, 2024). "When analyzed individually with IPA, the top FoxO dependent canonical pathways were most enriched for protein kinase A signaling, sirtuin signaling (which includes many OXPHOS and other mitochondrial genes), cancer-related, cardiac hypertrophy, PPARα/RXRα activation, and mitochondrial dysfunction." (PMID 35185597, 2021). "In addition, eNOS and glioma invasiveness signalling were more activated whereas LXR/RXR and PPARα/RXRα activation, GnRH (Gonadotropin Releasing Hormone) signalling, α-adrenergic, and cardiac hypertrophy signalling were significantly deactivated in aCDCs." (PMID 29915261, 2018). "Furthermore, several important regulators involved in cardiac hypertrophy were focused including HSF-1, ATGL, RXRα, and ERRα." (PMID 35479323, 2022).
liver fibrosis (7 papers, 2017 to 2025). "Activities of RXRa and AHR were also decreased; RXRa represses liver fibrosis by blocking hepatic stellate cell activation and proliferation, while AHR modulates inflammasome activation through inhibition of NF‐kB." (PMID 39605182, 2025). "The EtOH-fed+DNLA group displayed more activation of PPARα and PXR/RXRα than the EtOH-fed group, suppressed the upregulation of hepatic fibrosis signaling and death receptor signaling, and prevented the downregulation of the antioxidant action of vitamin C in the EtOH-fed group." (PMID 36359319, 2022). "In addition, retinoid X receptor α (RXRα) is an important nuclear receptor that plays a key regulatory role in liver fibrosis." (PMID 36553468, 2022).
non-small cell lung carcinoma (7 papers, 2019 to 2024). A group of at least three distinct histological types of lung cancer, including non-small cell squamous cell carcinoma, adenocarcinoma, and large cell carcinoma. "In contrast, downregulation of nuclear receptors, such as RXRα, has been documented in a variety of tumours, including non-small cell lung cancer." (PMID 39769410, 2024). "Accordingly, RNAi-mediated knockout of RXRα increases the induction of Nrf2-regulated antioxidant gene expression, and overexpression of RXRα in non-small cell lung cancer A549 cells leads to Nrf2 downregulation and increases sensitivity to therapeutic drugs." (PMID 36552553, 2022). "It has been reported that RXRα is down-regulated in thyroid cancer, stomach cancer and non-small-cell lung cancer, indicating that RXRα may function as a tumor suppressor." (PMID 37735649, 2023). "Retinoid-X-receptor alpha (RXRA) ligand bexarotene in combination with chemotherapy was more effective associated with better survival, and improved response in refractory cutaneous T-cell lymphoma (CTCL), metastatic breast cancer and non-small cell lung carcinoma (NSCLC)." (PMID 37324449, 2023).
bladder tumors (6 papers, 2017 to 2024). "Recurrent activating mutations of PPARγ and RXRα have been linked to pro-tumorigenic PPARγ/RXRα pathway activation in luminal bladder tumors." (PMID 39695138, 2024). "RXRα S427F/Y and PPARγ-overexpressing bladder tumors were significantly associated with suppression of immune infiltration and inflammation-related pathways." (PMID 28740126, 2017). "MCB6C is an organoid line we derived from a carcinogen-induced bladder tumor and lacks RXRA mutation." (PMID 29143738, 2017). "The S427F RXRA mutation predominantly occurs in bladder tumors." (PMID 30176882, 2018). "The upregulation of PPARγ/RXRα transcriptional activity has emerged as a key event in luminal bladder tumors." (PMID 30651555, 2019). "Using the conventional Sanger’s method, we sequenced the PPARG and RXRA exons in 359 bladder tumors (199 of which were NMIBCs) from our CIT series of tumors (carte d’identité des tumeurs) and from a bank of samples collected at Strasbourg hospital, and in 25 bladder cell lines." (PMID 30651555, 2019). "Our study reveals genomic alterations of PPARG that lead to pro-tumorigenic PPARγ/RXRα pathway activation in luminal bladder tumors and may open the way towards alternative options for treatment." (PMID 30651555, 2019). "Given this crucial role of the PPARγ/RXRα pathway in bladder tumors, in this work, we search for other genetic alterations that could drive its activation in both NMIBC and MIBC." (PMID 30651555, 2019). "No mutations in a known oncogene or tumor suppressor gene are shared by all three tumors; however, the primary bladder tumor and the lung metastasis share known oncogenic mutations frequently found in bladder tumors, such as mutations in the KMT2D and RXRA genes." (PMID 30176882, 2018). "RXRA, which encodes retinoid X receptor alpha (RXR-alpha), is mutated in 10% of bladder tumors." (PMID 30176882, 2018).